MPHOSPH8 (M-phase phosphoprotein 8)
Description:
Heterochromatin component that specifically recognizes and binds methylated 'Lys-9' of histone H3 (H3K9me) and promotes recruitment of proteins that mediate epigenetic repression. As part of the HUSH complex, promotes epigenetic repression of mobile genetic elements, such as retroviruses and transposable elements: the HUSH complex mainly represses LINE-1 (L1) retrotransposons that are still capable of transposition. Silencing events often occur within introns of transcriptionally active genes, and lead to the down-regulation of host gene expression. MPHOSPH8 mediates recruitment of the HUSH complex to H3K9me3 sites: the HUSH complex is recruited to genomic loci rich in H3K9me3 and is required to maintain transcriptional silencing by promoting recruitment of SETDB1, a histone methyltransferase that mediates further deposition of H3K9me3, as well as MORC2, a chromatin remodeler that compacts chromatin. The HUSH complex is also involved in the silencing of unintegrated retroviral DNA by being recruited by ZNF638: some part of the retroviral DNA formed immediately after infection remains unintegrated in the host genome and is transcriptionally repressed. As part of the HUSH2 complex, promotes epigenetic repression of interferon-stimulated genes. Binds H3K9me and promotes DNA methylation by recruiting DNMT3A to target CpG sites; these can be situated within the coding region of the gene. Mediates silencing of E-cadherin (CDH1) and protocadherin genes in the nervous system.
Synonyms: Twa3; MPP8; HSMPP8
Tractability: Antibody: its Gene Ontology location is reachable by antibodies, with high confidence. PROTAC: ubiquitination databases record sites on it; its protein half-life has been measured.
Target class: Epigenetic regulator; Reader; Methyl-lysine/arginine binding protein; Chromodomain
Gene: Protein-coding gene on chromosome 13 (19,633,659 to 19,673,441, forward strand). Ensembl gene ENSG00000196199.
Subcellular location: Nucleus; Chromosome
Subcellular location (Human Protein Atlas): Nucleoplasm; Cytosol; Plasma membrane
Pathways (Reactome):
Cell-Cell communication: Negative Regulation of CDH1 Gene Transcription
Gene expression (Transcription): Regulation of endogenous retroelements by the Human Silencing Hub (HUSH) complex
Gene Ontology:
Molecular function: chromatin binding; histone H3K9me2/3 reader activity; protein binding
Biological process: constitutive heterochromatin formation; negative regulation of gene expression via chromosomal CpG island methylation; negative regulation of gene expression, epigenetic; negative regulation of type I interferon production; transposable element silencing by heterochromatin formation
Cellular component: chromatin; chromosome; cytoplasm; heterochromatin; HUSH complex; HUSH2 complex; nucleoplasm; nucleosome; nucleus
Genetic constraint (gnomAD): Loss-of-function variants: 36 observed, 74.85 expected, observed/expected ratio (o/e) 0.48, 90% interval 0.37 to 0.63. The upper end of that interval is the gene's LOEUF score, 0.63, which puts it in group 2 of 6, group 1 being the genes least tolerant of losing a copy. Missense variants: 835 observed, 978.54 expected, observed/expected ratio (o/e) 0.85, 90% interval 0.81 to 0.9. Synonymous variants: 354 observed, 364.46 expected, observed/expected ratio (o/e) 0.97, 90% interval 0.89 to 1.06.
Homologues: Orthologues: chimpanzee MPHOSPH8 (99% identical), macaque MPHOSPH8 (97% identical), rabbit MPHOSPH8 (83% identical), guinea pig MPHOSPH8 (79% identical), pig MPHOSPH8 (79% identical), mouse Mphosph8 (78% identical), tropical clawed frog mphosph8 (56% identical), zebrafish mphosph8 (45% identical), Drosophila melanogaster CG9121 (9% identical). Paralogues in human: ASB14 (12% identical), ASB15 (11% identical), ASB18 (11% identical), ASB10 (10% identical), ASB16 (10% identical), ASB3 (9% identical), ASB4 (8% identical).
Diseases named in the same sentence as MPHOSPH8 in open-access papers:
MPHOSPH8 is named in the same sentence as 15 diseases in open-access papers, as found by Europe PMC text mining. Sharing a sentence is not in itself a finding about the gene and the disease. The quoted sentences say what the papers report.
hearing loss (1 paper, 2024). "These high priority genes, including MPHOSPH8, MYO18A, TRIOBP, OTOGL, TNC, and MYO6, were previously implicated in hearing loss, balance, and cochlear function, and were significantly enriched in common variant studies of hearing loss." (PMID 38943082, 2024).
lung carcinoma (1 paper, 2022). "In lung carcinoma mice models, it has been reported that low expression levels of MPHOSPH8 are linked to sensitization to anti-PD-1/CTLA-4 therapies, implying a feasible association of this epigenetic regulator and the suppression of the immune evasion." (PMID 35562916, 2022).
cancer (7 papers, 2020 to 2024). A tumor composed of atypical neoplastic, often pleomorphic cells that invade other tissues. "One cancer-associated gene (MPHOSPH8) was upregulated in samples infected with M.BCG relative to those infected with P.BCG, whereas three genes were downregulated in M.BCG (MIR31HG, SAA1, and TRIML2)." (PMID 35562916, 2022). "The first case concerned a nuclear protein member of the human silencing hub (HUSH) complex involved in epigenetic repression, encoded by Mphosph8 and frequently downregulated in diverse cancers, leading to DNA damage." (PMID 36430209, 2022).
tumor (3 papers, 2011 to 2025). "Using data from the National Cancer Institute Clinical Proteomic Tumor Analysis Consortium (CPTAC) we further demonstrated that ZNF638, TASOR, MPHOSPH8, SETDB1 proteins were significantly enriched in GBM versus normal brain tissue." (PMID 40091830, 2025).
infection (2 papers, 2022 to 2025). The state of being infected such as from the introduction of a foreign agent such as serum, vaccine, antigenic substance or organism. "Overall, the differential expression of MPHOSPH8, MIR31HG, SAA1 and TRIML2 could show us the subtle changes that occur in the infection between M.BCG and P.BCG." (PMID 35562916, 2022).
MPHOSPH8 also shares sentences with these, for which no sentence is quoted: acute myeloid leukemia (1 paper); Ataxia (1); breast carcinoma (1); deafness (1); hearing (1); migraine (1); myeloid leukemia (1); teratoma (1); Vertigo (1); viral infection (1).